MTOR (mechanistic target of rapamycin kinase)
Diseases named in the same sentence as MTOR in open-access papers (continued):
Sharing a sentence is not in itself a finding about the gene and the disease.
cancer (continued). "The phosphoinositide 3-kinase-Akt-mammalian target of rapamycin (PI3K-Akt-mTOR) signaling pathway, commonly activated in cancer, including AML, contributes to the maintenance of glycolysis by translational and post-translational regulation of metabolic enzymes." (PMID 37520325, 2023). "The mTOR and ERK pathways are potential therapeutic targets for many types of cancer." (PMID 37894790, 2023). "Thus, we concluded that triple-inhibitor treatment targeting mTOR, AKT and the MAPK pathway efficiently abolished cell proliferation and substantially eradicated tumor cells by apoptosis in different 3D cancer model systems." (PMID 36675180, 2023). "Moreover, the WNT, MAPK, MTOR, and NOTCH signaling pathways were all remarkably activated in cancer stem cells (CSCs) of HCC, which contributed to metastasis and poorly differentiated with the worse prognosis." (PMID 37903971, 2023). "In addition, propofol downregulated SIRT1 in cancer and inhibited the Wnt/β-catenin pathway and PI3K/AKT/mTOR pathway." (PMID 37490168, 2023). "In detail, an irregular function of PI3K/Akt/mTOR determines an increased expression of fusin, which subsequently stimulates C-X-C chemokine receptor type 4 (CXCR-4)-related STAT3; this cascade of signals allows the maintenance of stemness in cancer cells." (PMID 37240821, 2023). "Therefore, mTOR, STAT3, and CD24 were thought to represent promising and validated targets for the inhibition of cancer growth." (PMID 37919766, 2023). "Given the inhibitory effect of DIS3L2 KD in cell viability, we explored a potential target of DIS3L2 among genes that clustered in the mTOR pathway, and we found AZGP1, whose mTOR inhibitory activity has been previously documented in different cancer types, including CRC." (PMID 37340282, 2023). "Despite the low number of DEGs, several molecular pathways were also differentially regulated in clams exposed to site I compared to the control group, including “pathways in cancer”, “interferon response”, “PI3K/AKT/MTOR signalling” and “WNT signalling pathway”." (PMID 37880625, 2023). "Interestingly, PD-L1 has been reported to mediate cancer cell intrinsic functions in cold tumours through mTOR activation, and IMPDH2 promotes proliferation and migration through mTOR activation, suggested to be downstream of B7-H3." (PMID 37444640, 2023). "Hence, targeting mTOR, and mTOR- mediated signals like PI3K and Akt using plant-derived compounds can develop a promising therapeutic tool to fight cancer." (PMID 36737760, 2023). "In addition, it revealed anti-cancer effects on cancer cells by regulating a number of molecular factors involved in signaling pathways, such as PI3K/Akt/mTOR, Wnt/β-catenin, and MAPK/ERK1." (PMID 36926328, 2023). "The results of experiments performed years ago showed that inhibitors of the mTOR pathway have a negative effect on tumor cells, which sparked interest in the development of a class of drugs called mTOR inhibitors as anti-cancer therapies." (PMID 38201496, 2023). "Not surprisingly, mTOR and TrxR activation, as well as ER stress, are targets for drug development to interfere with the adaptation of cancer cells to hypoxia and nutrient shortage and to develop drug resistance." (PMID 37443747, 2023).
cancer (continued). "Phosphorylation of FLNA at S2152 was shown to occur by mTOR and by IGF-1 in cancer cells." (PMID 37457922, 2023). "In HNSCC, the PI3K/AKT/mTOR pathway is upregulated in over 90% of both HPV positive and negative carcinomas, and upregulation of this pathway is associated with resistance to radio- and chemotherapy." (PMID 37488620, 2023). "Some studies have reported that resveratrol can downregulate P-gp expression by inhibiting the PI3K/Akt/mTOR signaling pathway and subsequently reduce the drug resistance of cancer cells, suggesting that the PI3K/Akt/mTOR signaling pathway is closely related to drug resistance." (PMID 34981275, 2022). "As an anti-cancer agent, metformin mediated its activity via the AMPK/mTOR pathway." (PMID 36233373, 2022). "To speculate, our 6GPS may show predictive potential for cancer therapies, particularly for compounds acting through anti-proliferative mechanisms, like CDK-, Aurora kinase, or RAF/MEK/mTOR inhibitors." (PMID 35995935, 2022). "The most widely studied cancer signalling pathways include PI3K, AKT/PKB, and mTOR; these may significantly affect the increased transcription process connected with cellular proliferation, distant therapy results, and contribute to chemosensitivity." (PMID 35276890, 2022). "This state was inducible by inhibition of a mTOR dependent negative feedback loop in patient-derived cancer organoids." (PMID 35668108, 2022). "The ERK (extracellular signal regulated kinase) and mTOR (mammalian target of rapamycin) pathways are recognised key coordinators of the EMT process and cell migration during cancer metastasis, and both pathways can mediate the intracellular signals of OTR and EGFR independently." (PMID 35884900, 2022). "In addition, several signaling pathways related to cell transformation and cancer development, such as PDGF signaling, mTOR signaling, and PTEN signaling, were also found to be modulated." (PMID 35590368, 2022). "The functional enrichment analysis identified several pathways notoriously known to be crucial in cancer development and progression such as MAPK, PI3K/AKT/mTOR, RAS, ErbB, and HIF-1 signaling pathways as well as pathways involved in adaptive immunity in both TCGA-LUAD and TCGA-LUSC cohorts." (PMID 36139593, 2022). "Additionally, sufficient studies have suggested that SETD2, BAP1, mTOR, MUC16, HMCN1, KDM5C, ARID1A, and PTEN are intimately tied to prognosis and immune response in cancers." (PMID 35936012, 2022). "While awry mTOR signaling is an established event in HCC, the role of increased and decreased mTOR directly interacting with eIFs in cancer development has not been fully disclosed." (PMID 35159342, 2022). "In contrast, slight to no decrease in cytoplasmic mTOR was observed in cancer cells upon miR-99b-5p transfection." (PMID 36077039, 2022). "The mTOR signaling pathway, as a classic targeted molecule for the systemic therapy of RCC, has also been shown to promote and regulate the proliferation and invasion of cancer cells and is regulated by ECHS1, a key enzyme in fatty acid metabolism." (PMID 36591111, 2022). "In addition to autophagy, abnormal activation of PI3K/AKT/mTOR signalling has also been found to regulate apoptosis, chemoresistance, EMT and metastasis in various types of human cancers." (PMID 35166018, 2022). "The angiogenesis pathway, the PI3K/Akt/mTOR pathway and glucose metabolism are under thorough investigation in studies, but currently there is no approved targeted therapy for this cancer beyond hormonal therapy." (PMID 36139659, 2022). "We are aware that VitD/VDR has been suggested to affect various cancer-relevant signaling pathways, such as Akt- and/or mTOR, which we did not analyze in detail here." (PMID 36291915, 2022). "However, more changes in genes from cancer-signaling pathways such as MAPK and PI3K/AKT/mTOR and immune response/immune-checkpoint components that were associated with AI-resistant tumors and differential outcome were observed in the NeoAI study." (PMID 34965950, 2022).
cancer (continued). "It has been shown that autophagy exhibits a controversially cytoprotective or cytotoxic role in cancer radiation treatment, suggesting that dual inhibition of PI3K/mTOR may preferably promote radiosensitivity via an sautophagy-mediated pathway." (PMID 36555391, 2022). "Interestingly, mTOR serves as an activator of AKT, so a positive feedback loop can be formed between AKT and mTOR, thus promoting the proliferation and migration of cancer cells." (PMID 36059961, 2022). "It is of interest to test whether combinations of mTOR inhibitors, CDK inhibitors, and translation initiation factor inhibitors trigger a durable cell cycle arrest for the treatment of cancer cells." (PMID 35805935, 2022). "While the contribution of EIF1AX to tumorigenesis and cancer progression is not clear, EIF1AX has been found to have links to cancer-related signaling pathways including PI3K/AKT/mTOR and Ras/ERK signaling pathways, as well as oncogene c-myc." (PMID 36589683, 2022). "Water-soluble rapamycin analogues (temsirolimus, everolimus), ATP-competitive mTOR inhibitors (MLN0128, AZD2014, PP242), and dual PI3K/mTOR inhibitors (NVP-BEZ235, LY3023414, PQR309, XH00230381967, SN20229799306, GSK2126458, PKI-587) have been used to treat a variety of cancers." (PMID 36686771, 2022). "However, GSEA identified several cancer-related signaling pathways including INSULIN, MTOR, and PPAR pathways that were enriched in the low-ADAMTS14 expression group." (PMID 35572505, 2022). "The combination of the mTOR inhibitor temsirolimus (CCI-779) with chemotherapy (docetaxel) resulted in a strong antitumor activity in breast (MDA-MB-468) and prostate (PC3) xenografts and cancer cells." (PMID 36232388, 2022). "In addition, reduced AKT phosphorylation leads to inactivation of mTOR, P70S6 kinase 1, and 4EBP1, preventing protein synthesis in cancer cachexia." (PMID 36105371, 2022). "In addition, the mTOR and PI3K pathways can lead to resistance to cancer cell apoptosis and induce EMT." (PMID 35745875, 2022). "In addition, mTOR inhibitor everolimus can effectively inhibit the level of p-S6, thereby reversing the resistance of HER2-mutant cancers to neratinib and exerting anti-tumor effects." (PMID 35596155, 2022). "There are many signaling pathways, mediators, and downstream signaling proteins reported in angiogenesis-induced cancer: platelet-derived growth factor (PDGF), VEGF, fibroblast growth factors (FGF), hepatocyte growth factor (HGF), TKs, PI3K, MAPK, mTOR, Ras, and Raf." (PMID 36077338, 2022). "Luteolin has been found to be effective and exert an inhibitory effect on the proliferation, migration, and invasion of different cancers via acting on and altering the PI3K/AKT, mTOR (the mammalian target of rapamycin), ERK, and p38 signaling pathways and their associated molecules." (PMID 36358791, 2022). "Although data analysis from TCGA RNA-seq data has demonstrated an overall lower survival rate in cancers expressing high-level vs. low-level MTOR transcript, the differences were not statistically significant." (PMID 36077039, 2022). "Indeed, the rapamycin delivered in this study to suppress mammary mTOR activity is an FDA-approved immunosuppressive drug, used to treat several types of cancer and recognized for its longevity-inducing effect." (PMID 35731738, 2022).
cancer (continued). "This activity is relatively rare among PI3K/mTOR dual inhibitors, although various anticancer agents, such as curcumin and cisplatin, can trigger the nonapoptotic death of cancer cells." (PMID 35614940, 2022). "In the clinic, cancers have already developed resistance to approved Src kinase inhibitors, primarily through their ability to activate a panel of survival kinases like ERK1/2, PI3K/Akt and mTOR, requiring the need for combinational therapies." (PMID 35669422, 2022). "Furthermore, by targeting MYCN, a cancer-specific mTOR pathway inhibition occurs only in MNA-NB, thus avoiding the side effects of targeting mTOR in normal cells." (PMID 35490242, 2022). "Preclinical studies have shown that GBM cells exposed to niclosamide simultaneously downregulate multiple cancer cell signalling pathways, including NOTCH, mTOR, MAPK/ERK, and Akt-dependent signalling, leading to reduced cancer cell proliferation, viability, and migration." (PMID 36497413, 2022). "In cancer patients, the probable mechanism of function is based on the stimulation of adenosine monophosphate-activated protein kinase (AMPK) followed by the inhibition of PI3K, mTOR and ERK/STAT3 signaling pathways, the deprivation of energy support for cancer cells and their apoptosis." (PMID 35269636, 2022). "Indeed, a strict inter-connection between long-lasting/chronic inflammation and cancer onset exists, in which STAT3, NFkB and mTOR, pathways regulating both inflammation and cell proliferation, are key players." (PMID 35681760, 2022). "Thus, IRE1α-mediated UPR activates mTOR, which provides a survival signal for NOP56 KD KRAS-mutant cancer cells; conversely, mTOR inhibition leads to overwhelmed UPR and promotes apoptotic cell death by activating the JNK-FOXO3A-BIM axis." (PMID 35039048, 2022). "It coordinates with mTOR and MAPK signaling to regulate ferroptosis in cancer." (PMID 35359830, 2022). "In addition, another type of cancer, HNSCC, is characterized by hyperactivation of the mTOR pathway." (PMID 36428613, 2022). "We recently reported that MAPK4 is a key oncogenic kinase promoting cancer via non-canonical activation of AKT/mTOR independent of PI3K/PDK116." (PMID 35017531, 2022). "Whereas mammalian target of rapamycin (mTOR) was shown to be the major signaling molecule downstream of TSC2, targeting regulation of the PI3K/Akt/mTOR pathway has been proven effective in cancer therapies." (PMID 35178352, 2022). "Despite the efficacy of sirolimus derivatives in preclinical research as anti-cancer drugs, it is crucial to remember that inhibitors of mTOR have not shown to be as efficient as predicted." (PMID 36109789, 2022). "Considering that mTOR activators and NEC-1 (a necroptosis inhibitor) cannot be used in cancer therapy, we evaluated whether MFN2 exerted protective effects against sor-induced cardiac injury in vivo." (PMID 35154486, 2022). "In cancer, overexpression of the Akt and mTOR pathways play an important role in the progression of malignancies through the phosphatidylinositol-3-kinase (PI3K)/Akt/mammalian target of rapamycin (mTOR) pathway." (PMID 36232447, 2022). "To verify an on-target activity of the brain penetrant dual PI3K/mTOR inhibitor GNE-31722in vivo, we performed intravital microscopy and could demonstrate a specific PAM pathway inhibition in metastasizing cancer cells in the live mouse brain." (PMID 34216217, 2022). "In H&N cancer, gene editing may target the EGFR/PI3K/Akt/mTOR pathway for oncogenic organotypic fabrication." (PMID 35992863, 2022).
cancer (continued). "mTOR is a central regulator of autophagy and is related to cell proliferation and regulated by adenosine monophosphate-activated protein (AMP)–activated kinase (AMPK), which overactivates cancer cells." (PMID 35721116, 2022). "Only one study assessed the relationship between p-mTOR and the presence of AE, showing that the frequency of mTOR immunopositivity was 58% in non-AE, 63% in AE, and 77% in EAOC, with an increasing trend from benign and precursor lesions toward cancer." (PMID 35457244, 2022). "This, in turn, can enable combating widespread strategies used by cancer cells to resist the action of drugs, such as MET amplification or PI3K/AKT activation after targeted EGFR inhibition, PI3K/AKT compensation after mTOR inhibition, or MAPK/STAT3 cross-talk." (PMID 35913978, 2022). "Furthermore, MYC, mTOR, and HIF-1 are the main mediators regulating SLC transporters and glutamine synthase relative enzymes in cancers." (PMID 36052242, 2022). "In various cancers, the anti-tumoral effect exerted by the treatment with EGCG has also been evidenced by investigating the phosphatase and tensin homolog (PTEN), a regulator of the PI3K/Akt/mTOR signaling cascade." (PMID 35682754, 2022). "This study underpins the findings that, the down-regulation of CFHR expression in HCC cells may promote the cancer proliferation and tumor progression by exempting the inhibition of PI3K/Akt/mTOR pathway." (PMID 36338737, 2022). "Among the gene mutations acquired in the metastatic counterparts, the most frequently affected pathways (PIK3/AKT/MTOR, epigenetic, cell cycle, and WNT/β-catenin) might confer a selective advantage to cancer metastasis formation including hormone resistance." (PMID 35629078, 2022). "GSVA pathway analysis revealed differentially regulated cancer pathways between the three m5C-clusters, including KRAS-related pathways (MAPK-, mTOR-, EGF- and ERK-pathways), cell death pathways (TNFR1-, FAS- and death-pathways), and cancer-related pathways (Wnt-, Gleevec-, MET and CREB-pathways)." (PMID 36060802, 2022). "The EAAm-induced NEAA starvation activated the GCN2-ATF4 stress pathway, leading to ER stress, mTOR inactivation, and apoptosis in cancer cells, unlike non-cancer cells." (PMID 35367410, 2022). "In HCT116, K562, KB, and T47D cancer cells, DET (7.46, 4.02, 3.35, and 1.86 μg/mL, respectively) did not alter total AKT protein level, but significantly decreased the expression level of p-AKT and p-mTOR." (PMID 35408483, 2022). "The sensitivity of the phenocopy signatures in mutation-negative cancer cell lines was on par with DNA alterations for EGFR, BRAF, and MAPK, and better than DNA alterations for PI3K-AKT, PARP/HRD, ERBB2, MTOR, and JAK." (PMID 36253482, 2022). "The regulation of cancer cell development by PSMC genes has been studied in multiple cancers but rarely in LUAD, and their function as oncogenes was found to be correlated with dysfunctions in the cell cycle, PI3K/AKT/mTOR, MAPK, and EMT pathways." (PMID 36699466, 2022). "Because cancer cells have a high rate of glucose uptake and glycolysis, the competition for glucose suppresses calcium signaling, mTOR activity, glycolysis, and interferon (IFN)-production in T cells, leading to T cell exhaustion, reducing anti-cancer immunity, leading to immune evasion." (PMID 36072596, 2022). "Emerging studies have suggested that dual PI3K-mTOR inhibitors, which can block the entire PI3K-Akt-mTOR cascade, could achieve better and more robust anti-cancer efficiency." (PMID 35296639, 2022). "There are relatively many studies regarding the role of mTOR in cancer, but it is not much known about the role of mTOR in inner ear." (PMID 36661507, 2022). "Specifically, it has been demonstrated that NUCB2 contributes to cancer metastasis and a number of related processes, including EMT, endoplasmic reticulum (ER) stress, and cancer anorexia-cachexia syndrome, through regulation of the LKB1/AMPK/TORC1/ZEB1 and Akt/mTOR pathways." (PMID 36585713, 2022).